BARX2 (BARX homeobox 2)
Diseases named in the same sentence as BARX2 in open-access papers (continued):
Sharing a sentence is not in itself a finding about the gene and the disease.
tumor (continued). "IHC staining revealed that tumor xenografts with Barx2 knocked down showed higher expression of the cell proliferation markers Ki-67 and PCNA than controls, consistent with results of in vitro assays." (PMID 27533254, 2016). "In agreement with this fact, BARX2 expression reduces the tumor metastasis in xenografic tumors exhibiting highest metastatic potential." (PMID 27542258, 2016). "Through large-scale data mining, our study showed that BARX2 was differentially expressed between different normal and tumour tissues.BARX2 expression in LIHC tissues was significantly lower than that in corresponding controls, especially in patients with T2-4 stage disease." (PMID 37161008, 2023). "In addition, we analysed the expression of the BARX2 gene in 946 cell lines from 32 tumour types in the CCLE database." (PMID 37161008, 2023). "In addition, BARX2 partially abrogated the tumor-promoting impacts of circSHPRH knockdown on BCa cell proliferation, migration and invasion." (PMID 35200157, 2022). "Barx2 has also been reported to function as tumor suppressor in ovarian cancer." (PMID 36446858, 2022). "The expression of Human BarH-like homeobox 2 (Barx2), a tumor suppressor linked to the Wnt/β-catenin signaling pathway, was relatively lower in tumor samples than in adjacent samples in NSCLC patients, and low Barx2 expression is associated with poor prognosis." (PMID 36532721, 2022). "In this investigation, we attempted to explore whether BarH-like homeobox 2 (BARX2), a well-known tumor suppressor, had anti-cancer properties on NPC, and the possible mechanisms." (PMID 35037835, 2022). "This study suggests that miR-187 may contribute to OSCC progression through suppression of BARX2 expression and indicates the clinical importance of the miR-187–BARX2 cascade in tumor metastasis." (PMID 27542258, 2016). "Taken together, Barx2 is indeed involved in tumor progression, but its diverse functions in different cancers may be paradoxical." (PMID 27533254, 2016). "A reduced expression of BARX2 mRNA was found in tumor tissues relative to the surrounding tissue." (PMID 27542258, 2016). "In addition, we reveal that Barx2 suppresses Wnt/β-catenin signaling by decreasing expression of its downstream target genes, which mediate the pathway's tumor suppressor function in GC." (PMID 27533254, 2016). "All of these reports suggest that Barx2 works as a tumor suppressor gene." (PMID 27533254, 2016). "All of these findings support the hypothesis that Barx2 acts as a tumor suppressor inhibiting GC cell proliferation and invasiveness." (PMID 27533254, 2016). "Moreover, BARX2 is reported to be down-regulated in ovarian cancer and hepatocellular carcinoma, indicating that it normally acts as a tumor suppressor." (PMID 27542258, 2016). "Decreased Barx2 expression was highly correlated with tumor invasion (pT stage, P<0.001), LNM (pN stage, P=0.012), distant metastasis (M stage, P=0.044), advanced UICC stage (P<0.001), vascular invasion (P=0.002), nerve invasion (P=0.03), and histological differentiation (P<0.001)." (PMID 27533254, 2016). "Furthermore, our in vivo evidence provided that BARX2 overexpression could delay the tumor growth and lung metastasis in NPC." (PMID 35037835, 2022). "Interestingly, compared with the control cohort, the Barx2 knock-down cohort showed higher E-cadherin and lower vimentin expression in IHC staining of tumor xenografts, confirming our hypothesis that Barx2 acts as a cancer suppressor gene in GC." (PMID 27533254, 2016). "Barx2 may mediate ras/raf dependent transcription of the calcitonin gene via a ras/raf responsive promoter element and loss of Barx2-mediated differentiation may lead to loss of expression of the calcitonin marker, further resulting in MTC tumor progression." (PMID 27533254, 2016).
tumor (continued). "Downregulation of BARX2, partially by CGI hypermethylation, has been reported to correlate with enhanced aerobic glycolysis and aggressive behaviors of tumor cells and be indicative of poor prognosis." (PMID 37830163, 2024). "We also analysed the differential expression of BARX2 in LIHC patients from the TCGA dataset according to T stage and residual tumour status." (PMID 37161008, 2023). "Through bioinformatics analysis, we screened for BARX2, which was significantly poorly expressed in NPC tissues, and we hypothesized that it played a tumor suppressor role in NPC, which was verified by a series of in vitro and in vivo experiments." (PMID 35037835, 2022). "Finally, Western blot assay of Ras signaling pathway activity in tumor tissues showed that the phosphorylation levels of MEK and ERK were decreased in nude mice harboring BARX2 overexpression." (PMID 35037835, 2022). "In addition, Barx2 expression was significantly down-regulated in several human cancers including HCC, and Barx2 was identified as a tumor suppressor." (PMID 29069753, 2017). "In order to confirm the correlation between decreased Barx2 expression and tumor metastases or local relapse independent of clinical stage, we performed further overall survival analysis according to UICC stages and tumor relapse." (PMID 27533254, 2016). "A number of tumor related genes map in 11q distal region: EST1, CHK1, BARX2, OPCML, FLI-1, their role in tumor development and progression in JS is still unknown." (PMID 19267933, 2009). "In summary, decreased expression of Barx2 could serve as a novel independent prognostic biomarker for shorter overall survival independent of advanced clinical stage and tumor relapse." (PMID 27533254, 2016). "Together with the trend of a poorer DFS and OS in Barx2-negative tumors than in Barx2-positive tumors, we conclude that the decreased Barx2 expression likely correlates with tumor invasion and metastasis and provides a novel biomarker for a highly malignant GC phenotype." (PMID 27533254, 2016). "Most importantly, for the first time, we conclude that negative Barx2 staining predicts poorer survival in the advanced UICC stage and tumor relapse patients." (PMID 27533254, 2016).
cancer (11 papers, 2008 to 2023). A tumor composed of atypical neoplastic, often pleomorphic cells that invade other tissues. "By using the TIMER 2.0 database (based primarily on RNA-sequencing data from the TCGA cohort), we found that BARX2 expression was significantly associated with OS in patients with nine cancer types." (PMID 37161008, 2023). "Furthermore, in ESCA, KIRC and STAD, infiltration of cancer-associated fibroblasts was negatively correlated with the expression of BARX2." (PMID 37161008, 2023). "Taken together, these data suggest that BARX2 expression levels and prognostic significance are highly cancer dependent, requiring further confirmation of the specific role of BARX2 in each cancer." (PMID 37161008, 2023). "On the other hand, the prognostic value of BARX2 expression in cancer patients has been rarely reported thus far34." (PMID 37161008, 2023). "We observed that OSCC cell lines exhibited decreased BARX2 expression compared to that of NOK cells, possibly due to allele loss or targeting by endogenously-expressed miR-187 in cancer cells." (PMID 27542258, 2016). "To investigate the effect of Barx2 reduction on cancer biological processes in GC, we first compared Barx2 expression in seven GC cell lines and one healthy gastric mucosa cell line." (PMID 27533254, 2016). "These include a number of known or potential tumour suppressor genes (BCSC-1, CHEK1, ST14, ATM, P53AIP1), genes with proposed roles in cancer progression (BARX2), apoptosis (PIG8, P53AIP1) and oncogenesis (FLI1, ETS1), and a DNA damage-inducible gene (DDI1)." (PMID 18506147, 2008). "First, the role of BARX2 in tumorigenesis may be different among different cancers." (PMID 37161008, 2023). "However, the role of BARX2 as a transcription factor has been rarely investigated in cancers." (PMID 35037835, 2022). "This decreased expression could be caused by the combined effects of BARX2 deletion and the targeting effects of miR-187, since miR-187 was not greatly up-regulated in cancer cells relative to normal cells." (PMID 27542258, 2016). "Furthermore, the authors demonstrated that the expression level of this protein shows a negative correlation with the stage of cancer development (AJCC staging), and survival analysis reveals that Barx2 expression level is an independent prognostic factor for NSCLC patients." (PMID 37761972, 2023).
infectious disease (1 paper, 2023). A disorder directly resulting from the presence and activity of a microbial, viral, or parasitic agent in humans. "Dysregulation of BARX2 is associated with infectious diseases and cancer." (PMID 37161008, 2023).
BARX2 also shares sentences with these, for which no sentence is quoted: bladder urothelial carcinoma (1 paper); cholangiocarcinoma (1); colon cancer (1); diffuse large B-cell lymphoma (1); endocervical adenocarcinoma (1); head and neck squamous cell carcinoma (1); lung squamous cell carcinoma (1); lymph node metastasis (1); mesothelioma (1); oral carcinoma (1); ovarian serous adenocarcinoma (1); ovarian serous cystadenocarcinoma (1); pancreatic adenocarcinoma (1); paraganglioma (1); pheochromocytoma and (1); prostate adenocarcinoma (1); rectum adenocarcinoma (1); sarcoma (1); stomach adenocarcinoma (1); systemic lupus erythematosus (1); testicular germ cell tumour (1); thymoma (1); thyroid carcinoma (1); uterine corpus endometrial carcinoma (1); uveal melanoma (1).